BCAN (brevican)
Description:
May play a role in the terminally differentiating and the adult nervous system during postnatal development. Could stabilize interactions between hyaluronan (HA) and brain proteoglycans.
Synonyms: BEHAB; CSPG7; MGC13038
Tractability: Antibody: UniProt places it where antibodies can reach, with high confidence; its Gene Ontology location is reachable by antibodies, with high confidence; UniProt predicts a signal peptide or a membrane-spanning region.
Gene: Protein-coding gene on chromosome 1 (156,641,390 to 156,659,532, forward strand). Ensembl gene ENSG00000132692.
Subcellular location: Secreted; Secreted, extracellular space, extracellular matrix (Isoform 1); Membrane (Isoform 2)
Pathways (Reactome):
Disease: Defective B3GALT6 causes EDSP2 and SEMDJL1; Defective B3GAT3 causes JDSSDHD; Defective B4GALT7 causes EDS, progeroid type; Defective CHST14 causes EDS, musculocontractural type; Defective CHST3 causes SEDCJD; Defective CHSY1 causes TPBS
Metabolism: CS-GAG biosynthesis; CS/DS degradation; DS-GAG biosynthesis; Glycosaminoglycan-protein linkage region biosynthesis
Extracellular matrix organization: Degradation of the extracellular matrix; ECM proteoglycans
Gene Ontology:
Molecular function: protein binding; hyaluronic acid binding
Biological process: central nervous system development; skeletal system development; cell adhesion; synapse maturation
Cellular component: extracellular region; gel phase of interstitial matrix; Golgi lumen; lysosomal lumen; perineuronal net; synapse; extracellular matrix; glutamatergic synapse; membrane
Genetic constraint (gnomAD): Loss-of-function variants: 51 observed, 92.72 expected, observed/expected ratio (o/e) 0.55, 90% interval 0.44 to 0.69. The upper end of that interval is the gene's LOEUF score, 0.69, which puts it in group 2 of 6, group 1 being the genes least tolerant of losing a copy. Missense variants: 1,140 observed, 1,216.4 expected, observed/expected ratio (o/e) 0.94, 90% interval 0.89 to 0.98. Synonymous variants: 501 observed, 508.87 expected, observed/expected ratio (o/e) 0.98, 90% interval 0.91 to 1.06.
Homologues: Orthologues: chimpanzee BCAN (99% identical), macaque BCAN (97% identical), pig BCAN (90% identical), dog BCAN (88% identical), guinea pig BCAN (82% identical), rat Bcan (81% identical), mouse Bcan (80% identical), rabbit BCAN (71% identical), tropical clawed frog bcan (49% identical), zebrafish bcan (42% identical). Paralogues in human: ACAN (40% identical), VCAN (38% identical), NCAN (35% identical), HAPLN3 (16% identical), HAPLN1 (15% identical), HAPLN4 (14% identical), HAPLN2 (14% identical).
Diseases named in the same sentence as BCAN in open-access papers:
BCAN is named in the same sentence as 47 diseases in open-access papers, as found by Europe PMC text mining. Sharing a sentence is not in itself a finding about the gene and the disease. The quoted sentences say what the papers report.
glioma (40 papers, 2005 to 2025). A benign or malignant brain and spinal cord tumor that arises from glial cells (astrocytes, oligodendrocytes, ependymal cells). "Both PRO and MES eGBO‐derived tumors had broad expression of NOTCH1, which is commonly upregulated in glioma tumor‐initiating cells, and BCAN, which encodes an extracellular matrix protein found in human gliomas." (PMID 39836549, 2025). "Both brevican and tenascin-C are glycoproteins in the human brain that are overexpressed in glioma cells and associated with a later tumor stage." (PMID 37174618, 2023). "Three representative regions of C16 (LGG) were located at 1q22, and one of them was linked to the BCAN gene, which is considered a central factor in promoting glioma progression." (PMID 33166290, 2020). "This study indicates that the expression of brevican is associated with glioma cell adhesion, motility and tumor growth." (PMID 23253190, 2012). "Among the lecticans, BCAN overexpression is associated with glioma progression." (PMID 38791985, 2024). "However, several reports showed that BCAN is associated to invasive glioma and promotes glioma invasion after proteolytic cleavage and fibronectin binding, which support our data." (PMID 22901239, 2012). "Our studies suggested that brevican overexpression in glioma is associated with cancer progression, and therefore, brevican might be a useful biomarker of glioma." (PMID 23253190, 2012). "Across both adult and pediatric gliomas, BCAN (brevican) was the most abundantly detected proteoglycan." (PMID 40517137, 2025). "Regarding glioma cell migration, the extracellular matrix of the brain contains large quantities of specific molecules (e.g., neurocan and brevican (lectins) and phosphocan), which are secreted by astrocytes and oligodendrocytes and play a promigratory role." (PMID 39153088, 2024). "Malignant gliomas exhibit a unique brevican isoform and the brevican is critical for its proinvasive role in gliomas." (PMID 39194478, 2024). "It has been determined that the expression of BCAN is related to glioma cell invasion, adhesion, and tumor growth, and is a marker of the malignant degree of glioma." (PMID 38579169, 2024). "Integrins interact with ECM components, such as collagen, brevican, tenascin-C, fibronectin, and thrombospondin, which leads to the adhesion and migration of glioma cells." (PMID 35327982, 2022). "Other findings supporting the role of brevican cleavage by ADAMTSs in this type of tumor is that the highly invasive rat CNS-1 glioma cell line produces and cleaves brevican when grown as an intracranial graft." (PMID 33804223, 2021). "BCAN (Brevican) has been used as a target for immunotherapy in glioma, as its knockdown reduced late-stage glioma tumor aggressiveness." (PMID 32341755, 2020). "For another example, the representative region of C16 is 1q22, and its regulatory gene BCAN is essential in promoting the progression of glioma." (PMID 33166290, 2020). "For example, CSPGs brevican and versican display significantly higher levels of expression in glioma." (PMID 31803736, 2019). "In our previous mass spectrometry screening in the cerebrospinal fluid (CSF), we found brevican was overexpressed in glioma patients." (PMID 23253190, 2012). "In this study, we found that brevican was highly overexpressed in glioma and distinctively promoted cell adhesion ability." (PMID 23253190, 2012). "Interesting, malignant gliomas exhibit unique brevican isoforms, and brevican is critical for its proinvasive role in glioma." (PMID 23253190, 2012). "Evidence has shown that the coding sequence of the brevican gene in glioma is the same as the brevican gene found in the cortex of the normal brain." (PMID 23253190, 2012). "Similarly, brevican (BCAN), an extracellular matrix glycoprotein highly expressed in gliomas, was identified as a top hit." (PMID 40517137, 2025).
glioma (continued). "The ECM components form the cellular microenvironment and is often overexpressed in glioma cells; components such as hyaluronic acid, brevican, tenascin-C, fibronectin, thrombospondin, and specific integrins and receptors are known to promote cell adhesion and migration." (PMID 39874307, 2025). "Additionally, glioma cells produce proteins (e.g., brevican and tenascins), which increase their invasiveness." (PMID 39153088, 2024). "Studies have shown that brevican is overexpressed in patients who have these gliomas." (PMID 39194478, 2024). "BCAN is highly expressed in glioma and may promote the growth and cell motility of brain tumor cells." (PMID 36717900, 2023). "Brevican is one of five core proteins of CSPG in human glioma cell lines." (PMID 37231524, 2023). "Also, neural‐specific ECM molecule BEHAB/Brevican affects the invasion of glioma cells through the mediation of the extracellular matrix." (PMID 35569122, 2022). "However, other ADAMs with thrombospondin motifs (ADAMTS4, ADAMTS5) positively impacted the proliferation of glioma cells in vitro and potentially promoted their invasion by cleavage of brevican, a major component of brain tissue." (PMID 32346064, 2020). "In contrast, brevican knockdown inhibits the tumorigenicity of GBM cells suggesting that brevican may play an important role in glioma progression." (PMID 28670569, 2017). "Immunofluorescence of U-118 MG cultured within the 3D scaffold highlights expression of such CSPG molecules, with specific staining for the molecule brevican, a member of the lectican family, indicating that the glioma cell line expresses CSPGs when cultured within the 3D environment." (PMID 28011165, 2017). "In addition, the invasiveness of glioma cells correlates with brevican cleavage and the 53 kDa fragment is mainly responsible for this effect." (PMID 25225099, 2014). "Interestingly, among the genes that we found to be up-regulated in the HD-type, a few like GRIA2, BCAN and LPAR4 were already shown to be directly or indirectly implicated with glioma cell invasion." (PMID 22901239, 2012). "Similarly like laminin, brevican (BCAN) is a proteoglycan exclusive to the central nervous system and its expression is increased in GBM compared to healthy brain tissue, and has been associated with aggressiveness at the late stage of glioma progression." (PMID 37108208, 2023). "Furthermore, overexpression of various ECM components is observed in gliomas, including hyaluronic acid, brevican, tenascin-C, fibronectin and thrombospondin as well as specific integrins and other receptors interacting with ECM components, which lead to adhesion and migration of glioma cells." (PMID 36289737, 2022). "This analysis identified CSPG4, PTPRZ1, and BCAN as the most highly expressed and concordant ECM targets in adult gliomas, while GPC1, CSPG5, and TNR were the top concordant targets in pediatric gliomas." (PMID 40517137, 2025). "Both HAPLN3 and HAPLN4 can enhance the migration of glioma cells, while HAPLN4 can strengthen the mitogenic effect of BCAN." (PMID 38791985, 2024). "EGFR, BCAN, SOX2, PTN and CCN3 were found to be highly elevated in the glioma tumorous tissue with prominent fold change value, while other DE-ARGs, such as CLU, SCG3, showed no distinct expression alteration." (PMID 39033204, 2024). "Several ECM molecules involved in migration and invasion are proteoglycans (versican, brevican, cadherins) and glycoproteins (CD44, tenascin C, fibrinogen), which were found upregulated in higher grade gliomas." (PMID 37174618, 2023). "Glioma cells also secrete their own ECM components such as HA, brevican, tenascin-C, fibronectin, and thrombospondin, which enhance the mobility and invasiveness of glioma cells." (PMID 35448036, 2022). "The genes AQP4, BCAN, GFAP, PLP1, and S100B are part of the astrocytic, oligodendrocytic, or proneural glioma signatures." (PMID 34101353, 2021).
glioma (continued). "In 3D culture, the glioma cells positively expressed chondroitin sulphate proteoglycans (CSPGs), as revealed by anti-CSPG staining, and more specifically the CSPG brevican." (PMID 28011165, 2017). "Differentially expressed proteins in this early stage, low-grade gliomas, include important regulatory proteins such as EGFR, HNRNP K and BCAN." (PMID 27246909, 2016). "Therefore, the regulation of expression of brevican in glioma is not caused by mutation." (PMID 23253190, 2012). "Glioma cells in vitro and in situ express various ECM components that modulate their microenvironment and promote migration, including collagens, laminins, brevican, tenascin-C and SPARC." (PMID 19712474, 2009). "Cleavage of brevican, another member of the lectican family by ADAMTS-5 is functionally involved in glioma invasion in vivo." (PMID 17453002, 2007). "B/bΔg can localize to the extracellular surface of glioma cells, and its overexpression may promote tumor progression by interfering with the normal interaction of BEHAB/brevican to achieve novel cell‒cell interactions conducive to invasion." (PMID 37231524, 2023). "Moreover, brevican, a member of the lectican family of CSPG is upregulated in glio mas and its expression induces glioma invasion, which is especially enriched in the glioma stem cell (GSC) niche." (PMID 35204054, 2022). "Brain-enriched hyaluronan-binding protein (BEHAB) is an N-terminally cleaved bioactive fragment of brevican that is dramatically increased in human gliomas where it promotes glial cell motility and the aggressiveness of gliomas." (PMID 34409033, 2021). "Brevican (BCAN) which is known to bind to tenascin-R (TNR) with high affinity, is highly expressed in gliomas, initiating cells’ extracellular niche in human GBM tumors and is expressed by glioma initiating cells in vitro." (PMID 30626092, 2019). "Though BCAN knockdown does not affect glioblastoma initiating cell viability in vitro, it promotes glioma cell adhesion and migration in vitro and the knockdown of the gene inhibits both cell motility in vitro and tumorigenicity in vivo." (PMID 30626092, 2019). "We show that one such rearrangement, an microdeletion resulting in a fusion between Brevican (BCAN) and Neurotrophic Receptor Tyrosine Kinase 1 (NTRK1), is a potent oncogenic driver of high-grade gliomas and confers sensitivity to the experimental TRK inhibitor entrectinib." (PMID 28695888, 2017). "Studies have simulated four relatively rare chromosomal rearrangements with unknown oncogenic potential in human brain glioma and have found that one of the chromosomal deletions results in fusion between BCAN and NTRK1, which promotes the formation of highly invasive glioma." (PMID 32337264, 2020). "Although both full-length BCAN and BCAN HA binding domain (HABD) can promote invasion of glioma cells in non-neurogenic ECM, it seems that only HABD remains functional, promoting the invasion in brain ECM." (PMID 38791985, 2024).
glioblastoma (7 papers, 2012 to 2024). The most malignant astrocytic tumor (WHO grade IV). "In this regard, degradation of two well-known ADAMTS-5 substrates such as brevican and aggrecan facilitate tumor progression in glioblastoma and laryngeal carcinoma, respectively." (PMID 28099917, 2017). "However, the expression of brevican in patients with well-differentiated tumors was significantly higher than that of the patients with poorly differentiated tumors (anaplastic astrocytoma and glioblastoma) (P=0.005)." (PMID 23253190, 2012). "In this study, we correlated glioblastoma locations with the expression of five mesenchymal genes (VEGFC and its receptor FLT4, HGF and its receptor MET, and CHI3L1) and five proneural genes (PROM1, NOTCH1, DLL3, PDGFRA, and BCAN)." (PMID 26637806, 2016). "In particular, transcriptomic analyses showed a mesenchymal profile for periventricular glioblastoma stem-like cell line, with overexpression of VEGFC and CHI3L1 and a proneural profile for cortical glioblastoma stem-like cell line with overexpression of PROM1, DLL3, and BCAN." (PMID 26637806, 2016).
dementia (6 papers, 2020 to 2026). Loss of intellectual abilities interfering with an individual's social and occupational functions. "Our findings also covered well-known dementia-associated proteins, such as BCAN, CNTN5, and NCAN, along with identifying recently promising biomarkers, including IL18, MMP12, TNFSF12, and UNC5C, where these biomarkers presented the highest protein importance in their clusters." (PMID 40748327, 2025). "Our findings included well-known dementia-associated protein biomarkers, such as BMP4, CD200, MANF, PLXNB1, PLXNB3, and SMPD1 for AD and BCAN, NCAN, and THY1 for VD, as well as uncovering novel proteins associated with AD or VD." (PMID 39226887, 2024). "Among the top 20 proteins in the brain aging clock, those associated with at least two dementia phenotypes included glial fibrillary acidic protein (GFAP), neurofilament light chain polypeptide (NEFL), brevican (BCAN), kallikrein-6 (KLK6) and synaptotagmin-1 (SYT1)." (PMID 41299092, 2026). "Evidence indicate that the brain-specific protein, brevican, is proteolytically cleaved during neurodegeneration, hence positioning fragments of brevican as potential blood biomarkers of neurodegenerative diseases, such as dementia." (PMID 32559242, 2020). "For dementia, NEFL, BCAN, GFAP, and GDF15 were the main proteins influencing disease risk." (PMID 38016990, 2023).
brain tumor (4 papers, 2005 to 2023). "Down-regulated DEGs in recGBM included genes involved in cell proliferation (EGFR), possibly brain tumor cell growth (BCAN), deadenylation of mRNA, which is linked to neurodevelopmental disorders (CNOT2), and multi-drug resistance (ABCG2)." (PMID 37189838, 2023). "Down-regulated DEGs in recGBM were involved in cell proliferation (EGFR) and possibly brain tumor cell growth (BCAN), deadenylation of mRNA, which is linked to neurodevelopmental disorders (CNOT2), multi-drug resistance (ABCG2), and immune-related processes (GZMK)." (PMID 37189838, 2023).
mild cognitive impairment (4 papers, 2015 to 2024). "Taken together, this indicates a need to explore if lower BCAN levels also associate with post-stroke cognitive impairment and whether BCAN has a causal role in brain resilience and/or stroke recovery." (PMID 36418382, 2022). "In a proteomic analysis, NCAN, BCAN, CTSS, MSR1, MDGA1, and CPA2 were reported as upregulated in individuals with PTSD and comorbid mild cognitive impairment." (PMID 35625844, 2022). "In human superior frontal gyrus, levels of the brain-specific lectican, brevican, were significantly elevated in AD compared to non-cognitively impaired subjects, with a trend toward an increase in tissue from subjects with mild cognitive impairment." (PMID 26337292, 2015).
Stroke (4 papers, 2022 to 2025). Sudden impairment of blood flow to a part of the brain due to occlusion or rupture of an artery to the brain. "Notably, we found eight proteins shared by stroke and epilepsy (e.g., SH3BGRL3, PTPMT1), nine shared by epilepsy and VaD (e.g., DOCK7, BCAN), and ten by stroke and VaD (e.g., MTHFR, UVRAG), suggesting common pathogenic axes like inflammation and cellular stress." (PMID 40624693, 2025). "Ten proteins (including BCAN, NCAN, beta-NGF, SIGLEC1 and VWC2) were common to both the acute and convalescent stroke phase, but there were also differing examples." (PMID 40316737, 2025). "Likewise, while our analysis identified SPOCK1 and BCAN as ECM-related markers, other studies found ECM proteins like fibulin-1, fibronectin, and MMP9 elevated in stroke, highlighting consistent engagement of tissue remodeling pathways across stroke types." (PMID 41152969, 2025).
Alzheimer disease (3 papers, 2020 to 2024). A progressive, neurodegenerative disease characterized by loss of function and death of nerve cells in several areas of the brain leading to loss of cognitive function such as memory and language. "Genetic variation in the gene encoding A Disintegrin and Metalloproteinase with Thrombospondin Motifs 4 (ADAMTS4), which degrades the four members of the lectican family (including NCAN and BCAN), has been implicated in Alzheimer’s disease." (PMID 38762535, 2024). "Taken together, the evidence suggests NCAN, BCAN and their regulators as molecules-of-interest in Alzheimer’s disease." (PMID 38762535, 2024).
amyloid (3 papers, 2023 to 2024). "Since EVs s are a means of communication for neuronal cells, the impairment in the synaptic transmission induced by Aβ and p-tau could be related to the reduced levels of BCAN found in pEVs of patients with already established amyloidosis." (PMID 36788617, 2023). "BCAN, MDH1, PCOLCE and SELENBP1, to our knowledge, have not previously been implied in CAA/amyloid pathology." (PMID 38191511, 2024).